HMGB1 (high mobility group box 1)
Diseases named in the same sentence as HMGB1 in open-access papers (continued):
Sharing a sentence is not in itself a finding about the gene and the disease.
tumor (continued). "Administration of either HMGB1 inhibitors or genetic ablation of HMGB1 abolished HMGB1-mediated tumor cell proliferation." (PMID 29844348, 2018). "They demonstrated that protein HMGB1 expression in tumor tissue was only significant in tumor staging." (PMID 30245980, 2018). "Evaluation of murine and human VEGF by qPCR revealed variable VEGF mRNA levels within the tumor panel, as was seen with HMGB1 and HIF-1 alpha protein expression." (PMID 30123419, 2018). "Consistent with a previous report, our results showed that the expression of HMGB1 was significantly higher in tumor tissue than in peritumor liver tissue." (PMID 30526680, 2018). "Particularly, allogeneic tumor cell lysates obtained from heat shocked conditioned tumor cells contain elevated levels of danger signals (like released HMGB1 and translocated calreticulin), which improve DC maturation and tumor antigen cross-presentation." (PMID 29499656, 2018). "HMGB1 is key to cancer development, progression, and metastasis because it activates cancer cells, enhances tumor angiogenesis, and suppresses host anticancer immunity." (PMID 29546074, 2018). "Expression of HMGB1 is significantly elevated in tumor tissues and negatively correlated with miR-1284 expression." (PMID 29899164, 2018). "In this study, the HMGB1 expression in the HNSCC tumor and normal tissues was evaluated using IHC staining." (PMID 30245980, 2018). "Multivariate analysis using Cox proportional hazards model showed that tumor grade (p = 0.047) and HMGB1 (p = 0.011) were independent prognostic factors in CRC patients." (PMID 29844348, 2018). "In the current study, a positive correlation was observed between HMGB1 protein and mRNA levels in tumor samples." (PMID 30245980, 2018). "The overexpression of HMGB1 inhibits Rb-positive BC cells growth in vitro, also preventing growth in in vivo tumor models." (PMID 30049847, 2018). "The comparison of the expression levels of HMGB1 protein and mRNA in the tissue samples demonstrated that the expression of this gene in the tumor tissue was significantly higher than in the margin of the healthy tissue." (PMID 30245980, 2018). "Prolonged extracellular lifespan and activity of HMGB1 can sustain chronic inflammation and contribute to tumor growth, angiogenesis, and metastasis." (PMID 29636841, 2018). "Previous reports suggested that the interaction between HMGB1 and RAGE triggered the activation of NF-κB, MAPK, and MMP-2/MMP-9 signaling pathways, which are associated with tumor growth, invasion, and metastasis." (PMID 29850505, 2018). "Herein, we analyzed the protein expression of RAGE in irradiated HMGB1 WT and KO tumor cells, including HMGB1 WT tumor cells treated by supernatant of irradiated HMGB1 WT and KO tumor cells." (PMID 29844348, 2018). "We determined HMGB1 levels in the sera of tumor-bearing mice and found a distinct secretion profile." (PMID 30123419, 2018). "Tumor progression is often accompanied by appearance of a necrotic region that contains released HMGB1." (PMID 28969049, 2017). "The role of HMGB1 in cancer is complex and is likely to be tumour cell specific as well as contingent on the redox state of HMGB1, its subcellular localisation and the expression of corresponding ligands/binding partners." (PMID 29254158, 2017). "During tumor development, HMGB1 has been characterized as both a pro- and anti-tumoral protein by either promoting or suppressing tumor growth, proliferation, angiogenesis, invasion and metastasis." (PMID 28969092, 2017). "The finding outlined in elucidating the role of extracellular HMGB1 in regulation of tumor cell invasion and metastasis is controversial." (PMID 28969092, 2017). "ATP, CRT, and HMGB1 bind to their respective receptors on immature DCs to facilitate the recruitment of DCs into the tumor bed, the engulfment of tumor antigens by DCs, and optimal antigen presentation to T-cells." (PMID 28695111, 2017).
tumor (continued). "Gene expression profiling results of ECs isolated from freshly resected colorectal tumors, normal colon tissue and placenta showed that HMGB1 was a tumor angiogenesis gene." (PMID 28969092, 2017). "HMGB1 in necrotic tumour cell lysates increased ATP production, providing a direct link between the inflammation and tumour energy metabolism." (PMID 28039939, 2017). "The enhanced immunogenicity of R2016-killed tumor cells was strongly linked to the induction of CRT and HSPs on the surface of the dying tumor cells and the extracellular release of HMGB1." (PMID 28282460, 2017). "HMGB1 was detected predominantly in the nuclei, and its expression level in cancer tissues was significantly higher than that in paired adjacent non-tumor tissues." (PMID 29069735, 2017). "The ability of cytokines—as well as danger signals like HMGB1—to shift the immunoevasive tumor toward a state of damaged tissue engages the whole immune machinery to intervene against the neoplasia." (PMID 28638385, 2017). "Recent studies have demonstrated that the expression of HMGB1 in NSCLC tumour tissue is markedly increased compared with that in normal tissue." (PMID 28727734, 2017). "A variety of in vivo and in vitro studies suggest that HMGB1‐RAGE signalling plays an important role in tumour invasion and metastasis." (PMID 28039939, 2017). "The results indicated that HMGB1 signal generated two different immune effects during tumor development." (PMID 28968989, 2017). "Cancer cell death induced by conventional antineoplastic therapies elicits immune responses by release of tumor antigens, ATP and high mobility group box 1 (HMGB1)." (PMID 29064420, 2017). "Based on the previous indications that Carbenoxolone can act as an HMGB1 antagonist, levels of HMGB1 were analyzed in tumor tissues by immunohistology, showing lower HMGB1 levels in the treated tumors compared with the untreated group." (PMID 28415753, 2017). "Tumor-derived HMGB1 inhibited the cytotoxic anti-tumor CD8+ cells by potentiating regulatory IL-10-producing T cells." (PMID 28404891, 2017). "Released HMGB1 can either stimulate immune-mediated tumor death or contrarily induce a tumor-supportive inflammatory response, depending on its oxidation status." (PMID 29064420, 2017). "The dual immunological effect of HMGB1 on tumor therapy is also unexploited, which needs further exploration." (PMID 28968989, 2017). "In parallel, TLR7/8 stimulation also induced regulatory genes, such as IL-10, and anti-tumor factors, such as high-mobility group box 1 protein (HMGB1)." (PMID 29190907, 2017). "In nucleus, HMGB1 acts as a tumor suppressor via various mechanisms to sustain genome stability, while out of nucleus, it acts as either tumor supporter or tumor suppressor." (PMID 28969092, 2017). "Because it is an important DAMP, HMGB1-mediated immunogenic cell death enhances the effects of chemotherapy by promoting tumour cell death." (PMID 29246127, 2017). "It is demonstrated that irradiated tumor cells released HMGB1 can activate TLR4 on dendritic cells and lead to tumor elimination by tumor-specific T cells." (PMID 28969092, 2017). "Included in the NK genes up-regulated after CL097 activation was HMGB1, which can play an important role against tumor cells." (PMID 29190907, 2017). "In many cases, extracellular HMGB1 acts as a pro-tumor protein due to its cytokine, chemokine, and growth factor activity, whereas intracellular HMGB1 promotes drug resistance due to its proautophagic activity." (PMID 28374746, 2017). "Soluble RAGE is an endogenous truncated form of RAGE consisting of the extracellular domain of RAGE, which acts as a decoy to block HMGB1-RAGE signaling pathway in animal tumor models." (PMID 28969092, 2017). "This observed release of HMGB1 was an additional indicator that R2016 induced immunogenic cell death in these tumor cells." (PMID 28282460, 2017).
tumor (continued). "We found that miR-142 expression was negatively correlated with the expression of HMGB1 based on the results from 30 cases of tumor tissues (R2 = − 0.851, p < 0.001)." (PMID 27829233, 2017). "As HMGB1 inhibitor, GR impedes HMGB1 induced tumor cell proliferation, migration, blood vessels formation and inflammatory condition." (PMID 28969092, 2017). "As a multifunctional cytokine, HMGB1 plays a key role in tumor formation, metastasis and immune escape." (PMID 28968989, 2017). "In this study, by in vitro and in vivo experiments, we indicated that HMGB1 mediated tumor immune escape by promoting MDSC cell proliferation." (PMID 28968989, 2017). "Blockade of HMGB1-RAGE signaling has been observed to suppress tumor growth and metastasis in implanted tumors." (PMID 28969092, 2017). "HMGB1 is involved in multiple biologic process of cancer, such as tumor growth, tumor cell proliferation, invasion and metastasis." (PMID 28969092, 2017). "Previous studies have indicated that miR-200c acts as a tumour suppressor in various cancers by downregulating high-mobility group box 1 (HMGB1) and thereby suppressing EMT and metastasis." (PMID 28727734, 2017). "In tumor tissues, HMGB1—a ligand of TIM-3—is believed to act together with tumor-derived nucleic acids to gain access to endosomal vesicles and activate innate immune responses by DCs." (PMID 28300768, 2017). "TIM-3 also binds to the pleiotropic alarmin HMGB1 and suppresses antitumor immunity via interfering with the ability of HMGB1 to transport tumor-derived DNA to the endosomes of DCs." (PMID 28515726, 2017). "The HMGB1 immunohistochemical staining (IHC) of the tumour specimens was performed to determine the HMGB1 expression levels in the Plvx-sh HMGB1 and Plvx-HMGB1 groups in vivo." (PMID 29246127, 2017). "Antibodies of HMGB1 inhibit tumor angiogenesis in chicken embryo chorioallantoic membrane (CAM) model." (PMID 28969092, 2017). "To this end, we tested the effect of Carbenoxolone, an HMGB1 antagonist, on primary tumor growth and metastatic progression in several murine tumor models." (PMID 28415753, 2017). "For instance, extracellular HMGB1 is conducive to ICD-associated antitumor immunity in the early stages of chemotherapy, while it facilitates residual tumor cell survival in the late stages of chemotherapy." (PMID 28969092, 2017). "The result showed that with the down-regulation of HMGB1, the tumor growth was inhibited significantly and the mice survival was prolonged greatly." (PMID 28968989, 2017). "Overexpression of HMGB1 was observed in several cancers, and played significant roles in regulation of tumor growth, metastasis, and chemotherapy and radiotherapy resistance." (PMID 28376901, 2017). "Accordingly, neutralizing monoclonal antibody of HMGB1 should incorporate the fact that HMGB1/TLR4 signaling modulates inflammatory responses while HMGB1/RAGE signaling promotes tumor growth and metastasis." (PMID 28969092, 2017). "Taken these together, these reports suggest that HMGB1-primed TAMs in the necrotic region of a tumor can function both as an anti-tumor M1-like macrophage and as a CSC-generating macrophage." (PMID 28969049, 2017). "Currently, HMGB1 Ab, HMGB1 antagonist, HMGB1 inhibitor, and nucleic acid technology inhibit expression, secretion, and signal transduction of HMGB1 in tumor cells, which plays a key role in anti-inflammation therapy." (PMID 28968989, 2017). "Our study indicates that intracellular HMGB1 is a novel tumor suppressor of PDAC by sustaining chromosome stability and limiting pro-inflammatory nucleosome release and activity." (PMID 28374746, 2017). "In this study, Renca mouse model was established and the influence of HMGB1 on MDSCs was investigated by using HMGB1 antibody to downregulate the expression of HMGB1 in tumor-bearing mice." (PMID 28968989, 2017).
tumor (continued). "Further basic and clinical studies are warranted to exploit the explicit structure, location and partners of HMGB1, especially multiple functions of HMGB1 in regulating tumor cell survival and death." (PMID 28969092, 2017). "TIM-3 is highly expressed on tumor infiltrating DCs and actively competes with nucleic acids released from dying tumor cells to bind HMGB1, effectively inhibiting stimulation of the innate immune response by nucleic acids." (PMID 28300768, 2017). "The average tumour volume in the group of mice injected with sh-HMGB1 HepG2 was smaller than that in the group of mice injected with the sh-control HepG2 cells at all time points." (PMID 29246127, 2017). "When MDSCs were eliminated with Gr-1 antibody in vivo, the ability of the HMGB1 to promote tumor growth was severely impaired." (PMID 28968989, 2017). "It is also observed that endogenous HMGB1 increases mitochondrial RAGE expression, which is associated with tumor cell ATP production via MEK-ERK-MAPK pathway." (PMID 28969092, 2017). "Induction of autophagy by HMGB1 is important for tumor development and a novel target for cancer therapy." (PMID 29296182, 2017). "Extracellular HMGB1 can promote NFκB transportation to the nucleus and induce expression of inflammatory factor and tumor cell proliferation via TLR4 signaling pathway." (PMID 28969092, 2017). "By inhibiting caspase activity, increasing NF-κB activity and upregulating the cellular inhibitor of apoptosis protein-2, HMGB1 can inhibit apoptosis of tumor cells, thus promoting the occurrence and development of tumor." (PMID 28968989, 2017). "As potent stimulators of immune responses, HMGB1 potentiated A20 lymphoma-specific activation of immature dendritic cells with subsequent generation of tumor-specific cytotoxic T-lymphocytes and tumor cell lysis." (PMID 28422728, 2017). "Other studies have showed that the redox of HMGB1 plays an important role in tumor cell death and survival." (PMID 28969092, 2017). "TLR4 can also enhance tumor cell–platelet interactions, a function that is, at least in part, dependent on the release of endogenous ligand HMGB1 by tumor or damaged cells." (PMID 28894697, 2017). "High-mobility group box 1 (HMGB1) is a nuclear protein that is known to be secreted into plasma and other extracellular fluids from injured cells, activated macrophages, and tumor cells." (PMID 28536706, 2017). "HMGB1 and HSP70, the representatives of TLR2/4 ligands released from tumor cells, have been implicated in promoting the production of proinflammatory cytokines." (PMID 28415700, 2017). "The most plausible mechanism of this decrease in HMGB1 is that the tumor mass was reduced by vaccination." (PMID 28536706, 2017). "According to previous studies, several miRNAs were reported to inhibit HMGB1 expression to suppress tumor progress in many kinds of cancers." (PMID 28403886, 2017). "Here, we evaluate the role of HMGB1 in tumor development and attempt to reconcile the dual effects of HMGB1 in carcinogenesis." (PMID 28969092, 2017). "During anticancer therapy, HMGB1 favors to release into the extracellular milieu, which has positive effects on tumor relapse, such as stimulation of cancer cell proliferation, angiogenesis, cell motility and inflammation." (PMID 28969092, 2017). "In a mouse model of mammary tumors where animals were treated with an anti-HER2/neu antibody, the release of HMGB-1 was essential for antibody-mediated tumor regression." (PMID 28855903, 2017). "The release of HMGB1 was identified as a trigger for acute anti-neoplastic inflammation that was initiated against tumor cells during chemotherapy." (PMID 28404891, 2017). "This tumor cell killing was in parallel with the prominent increase in extracellular ATP release and HMGB1, underscoring the critical involvement of ICD as a potential mechanism in this gene therapy approach." (PMID 28122343, 2017).
tumor (continued). "Many cell types can actively release HMGB1, such as monocytes, macrophages, DCs, NK cells, endothelial cells and tumor cells." (PMID 28969092, 2017). "Meanwhile, it is confirmed that high mobility group box-1 protein (HMGB1) shows a high expression in many solid tumors and HMGB1 with high expression is involved in tumor immune escape." (PMID 28968989, 2017). "Some of the anti-tumor effects of EP were related to its ability to inhibit HMGB1 expression and/or secretion and to inhibit the HMGB1-RAGE signaling axis." (PMID 28186988, 2017). "For these patients, enhanced survival and disease control correlated with both increased anti-tumour T cell responses and enhanced serum levels of HMGB1, a marker of immunogenic cell death." (PMID 28536346, 2017). "The released HMGB1 will trigger the chronic inflammatory response, promote tumor cell survival, invasion and neoangiogenesis through activation of intracellular signaling." (PMID 27391431, 2016). "Stress-induced release of the damage-associated molecular pattern molecule high-mobility group box 1 (HMGB1) induces cytoprotective autophagy and once extruded into the extracellular matrix recruits regulatory T cells that reduce anti-tumor immunity." (PMID 27463016, 2016). "The stable knockdown of HMGB1 in HCCLM3 cells resulted in slower growth of xenograft in Balb/c athymic mice in tumor size and weight than those of the control ones." (PMID 26499944, 2016). "HMGB1 is constitutively expressed in the nucleus of tumor cells and can be released by inflammatory cells and by tumor cells." (PMID 27836008, 2016). "IL-12 is mainly produced by DCs in response to tumor-associated antigens or during the release of damage-associated molecular patterns (DAMPs) such as HMGB1, HSP, and calreticulin in the tumor microenvironment." (PMID 26745884, 2016). "Within HIF1α-positive tumour areas, large numbers of tumour cells displaying cytoplasmic HMGB1 expression were observed and double-labelling experiments identified numerous cells co-expressing HMGB1 and HIF1α." (PMID 27426915, 2016). "Treatment of DC with tumor supernatants increased the ability of DCs to stimulate T cell proliferation, and blockade of HMGB1 in the supernatants suppressed DC activity." (PMID 27177220, 2016). "Collectively, these findings support an important role of HMGB1 in cancer transformation, tumor growth and invasion." (PMID 27116470, 2016). "These include cell surface-exposed calreticulin and ATP and HMGB1 that are released by dying tumor cells following their exposure to certain genotoxic agents such as ionizing radiation (IR), doxorubicin and oxaliplatin." (PMID 27917193, 2016). "High peritumoral HMGB1 expression was positively correlated with recurrence (p = 0.001), tumor encapsulation (p = 0.019), and advanced BCLC stage (p = 0.036)." (PMID 27836008, 2016). "The pooled model also showed a significantly higher protein level of HMGB1 in NSCLC tissues than in para-tumor tissues using IHC methods (6 articles, pooled mean difference 3.87, 95% CI 2.66-5.62, Z=7.1, P=0.000)." (PMID 26840258, 2016). "Following sub-cutaneous injection, mice implanted with HMGB1-shRNA-transduced B16 clones exhibited significantly reduced tumour growth when compared to mice implanted with the same number of lamin-shRNA-transduced B16 clones." (PMID 27426915, 2016). "HMGB1 expression showed predominant cytoplasmic staining and sparse nuclear staining in tumor and paratumoral liver tissues." (PMID 27836008, 2016). "Extracellular HMGB1 has multiple pro-tumor roles in tumorigenesis, such as promotion of angiogenesis, evasion of apoptosis, inhibition of antitumor immunity, inflammation, promotion of tissue invasion and metastasis." (PMID 26840258, 2016).